CD4 (CD4 molecule)
Diseases named in the same sentence as CD4 in open-access papers (continued):
Sharing a sentence is not in itself a finding about the gene and the disease.
cancer (continued). "A study on 76 paraffin-embedded samples of VSCC found that CD8+ and CD4+ cells were present in both cancer cell nests and stroma, suggesting an immunological synergy, but their presence was not related to better survival." (PMID 33375467, 2020). "Abnormal levels of NK cell, CD8+ T cells, memory CD4+/CD4+, naïve CD4+/ CD4+, CD8+ HLA‐DR/CD8+, CD8+ CD38+/CD8+, and CD4+/CD8+ can be a potential blood biomarkers of cancer development." (PMID 32459060, 2020). "These publications were particularly focused on the impact of epigenetics on the formation of CAFs (cancer associated fibroblasts) and CD8 T cell exhaustion (TOX) but more data on CD4 T cell biology need to be collected." (PMID 32121394, 2020). "Both median age and median CD4 count at cancer diagnosis were lower for individuals diagnosed with an ADM than with an NADM, and for viral NADM compared to nonviral NADM." (PMID 32003460, 2020). "CD4 T cells play a major role in the anti-cancer response alone or with other effector cells such as CD8 T cells and NK cells." (PMID 32630460, 2020). "While Group 1 ILC subsets are considered to play an important role in cancer regulation due to their similarity to CD4 Th1 cells and production of IFNγ, their involvement and function in metastasis is rather unclear." (PMID 32625207, 2020). "Since PD-1 is closely associated with dysfunction of CD4+ and CD8+ T cells, the efficacy of the antibody against PD-1 is widely thought to be attributed to activation of T- cell in the treatment of cancer." (PMID 32131763, 2020). "CpG ODN, a TLR9 agonist, has been widely used as an adjuvant in cancer vaccines, because of its ability to enhance the capacity of Th1-type CD4+ T cell responses and antigen-specific CD8+ T CTL responses." (PMID 32823603, 2020). "Th1 CD4+ T cells are multifaceted, playing important roles in antiviral, antibacterial, and anti-cancer immune responses." (PMID 33374787, 2020). "The results demonstrated a strong positive correlation between HNF1B expression and the infiltration levels of B cells, CD8+ T cells, CD4+ T cells, macrophages, neutrophils and DCs in cancer." (PMID 33173410, 2020). "In this regard, we previously reported that PD-1 expression on both CD4+ and CD8+ T cells obtained from cancer tissue was upregulated in GC patients and the function of these PD-1-positive CD4+ and CD8+ T cells was severely impaired." (PMID 32131763, 2020). "In this study, we describe a peptide-based cancer vaccine platform that elicits both CD4+ and CD8+ T cell responses toward neoantigens." (PMID 33298945, 2020). "The less abundance of Temra cells in tumors based on scRNA‐seq analysis is consistent with previous observations by traditional flow cytometry analysis (identified as CD45RA+CCR7− CD4+ or CD8+ T cells) in multiple cancer types." (PMID 32272497, 2020). "Previous studies suggested that CD4+ T cells play a central role in initiating and maintaining anti-cancer immune responses." (PMID 32767974, 2020). "While T-cell immune stimulation has been studied in preclinical models of cancer, these studies have focused on changes in CD4 + T-cell viability in the presence of cancer cells." (PMID 33292267, 2020). "CD8+ and CD4+ conventional T (Tconv) cells drive immune activation and promote clearance of infections and cancer." (PMID 33144667, 2020). "Tregs are CD4+ T cells known as immune suppressors that are activated in cancer tumors, which reduce the immune response against cancer cells." (PMID 32326073, 2020). "In the context of cancer, CD4+ T cell subpopulations, immunosuppressive regulatory (Tregs), and pro-inflammatory T helper 17 (Th17) cells, which normally act to fine-balance the adaptive immune responses, promote cancer progression and metastasis." (PMID 32570805, 2020). "Universal cancer peptide-based vaccine (UCPVax) is a vaccine directed towards universal cancer peptide telomerase to activate CD4 helper T lymphocytes." (PMID 32448366, 2020).
cancer (continued). "The activated CD8+T cells are associated with the prognosis of many cancers, including RCC, and the infiltrating CD4+ T cells can regulate RCC cell proliferation by modulating." (PMID 32633782, 2020). "Studies have shown that YAP promotes growth and proliferation of cancer cells, and more recently that it also enhances differentiation of the immunosuppressive T regulatory (Treg) subset of CD4+ cells." (PMID 32322254, 2020). "CD4+ T cells that differentiated into Th1 cells have been shown to sustain the cancer cytotoxic functions of CD8+ T cells." (PMID 33086518, 2020). "The expansion of TERT-specific CD4 T cells in the peripheral blood of cancer patients correlates with a more favorable outcome of disease." (PMID 32630460, 2020). "Univariable logistic regression analysis indicated that old age, comorbidity of malignant tumor, neutrophilia, lymphocytopenia, increased CRP levels, lower CD4+ T cell count, and decreased C3 levels were associated with death." (PMID 32746940, 2020). "For example, regulatory T cells (Tregs), a subset of CD4+ T cells recruited by cancer cells to evade the immune system, can be recruited via EV-signals sent out by cancer cells." (PMID 31817101, 2019). "While these oncology studies are of great interest and medical importance, we sought to systematically investigate the landscape of PMT inhibition in a non-cancer setting, namely CD4+ T helper (Th) cell differentiation." (PMID 30604761, 2019). "JAWS II DC were capable of activating the CD4+ T cells to produce significant levels of IL-2 when co-cultured with SMG E.G7 cancer cells as compared to co-culture with Static E.G7." (PMID 31602007, 2019). "Overall, cancer patients showed a significantly higher baseline percentage of CD4 THD cells than healthy controls (P < 0.001)." (PMID 31273938, 2019). "The importance of CD4+ cells for establishment of an anti-cancer immune response is illustrated by two clinical trials with CD4+ cells." (PMID 30232514, 2019). "The activation of the ICOS pathway plays a key role in activating the expansion of Treg and the release of IL-10 by secretion from memory CD4+ T cells, both of which create an immunosuppressive environment for cancer growth." (PMID 31143539, 2019). "As our previous reported which was published in Cancer Science 2014 February, CD4+ T cell and CD8+ T cell were identified by IHC in tissue samples." (PMID 31777600, 2019). "DAMPs not only prime cancer-killing CD8+ T cells for the secretion of interferon γ (IFNγ), but also anti-cancer CD4+ T cells for the secretion of IFNγ and IL-17A." (PMID 31739582, 2019). "Expansion of effector perforin+FasL+CD4+T cells has been described in cancer patients, during neo-adjuvant chemotherapy, in proportion to clinical response." (PMID 31366386, 2019). "In the shown analysis, regulatory T cells accounted for ~50% of all CD4+ T cells, a phenotype that potentially contributes to anti-cancer therapy resistance." (PMID 31417550, 2019). "As expected, only 19305DP-TCR-transduced CD8+ T cells showed strong cytotoxicity in vitro, although CD4+T cells significantly induced apoptosis of cancer cells after overnight coculture." (PMID 30626427, 2019). "Conversely, RGMB levels positively correlated with resting memory CD4+ T cells (28 of 33 cancers, p = 2.6 × 10−4)." (PMID 31061392, 2019). "Numerous other manuscripts have also noted the presence of potential CD4+CD25+ Treg cells in multiple types of cancer including melanoma, pancreatic cancer and breast cancer." (PMID 31058083, 2019). "CD4+/CD25+/FOXP3+ Treg contributes to immunosuppression and cancer progression by reducing the anticancer immunity of CD4+ or CD8+ effector T cells." (PMID 31815635, 2019). "Frequency of CD4+CD45RChigh T cells was positively correlated with those of CD8+CD45RChigh (p<0.0001), suggesting that recipients with high AR risk display a low cancer risk." (PMID 30925186, 2019).
cancer (continued). "The E.G7 cancer cells were able to suppress dendritic cell activation of OVA-specific CD4+ T cell IL-2 production relative to T cell activation in the absence of E.G7." (PMID 31602007, 2019). "Our results support the positive effects of higher baseline peripheral CD8+ T-cell proportions and lower CD4:8 ratios in cancer cases, especially among patients with HNSCC." (PMID 30991692, 2019). "FoxP3+ regulatory T cells (Tregs) have a prognostic relevance in cancer, high Treg/CD4 T cell ratios correlate with more aggressive cancers." (PMID 31659168, 2019). "CD8+ and CD4+ T cells are important components of the immune system, which has been proved to have strong correlation with cancers." (PMID 30906311, 2019). "In light of these results, we propose that human DBMSCs are immunostimulatory cells with the potential to target cancer cells by acting on macrophages to enhance macrophage anticancer activities either directly or indirectly through CD4+ T cells." (PMID 30781712, 2019). "Taken together, our studies show that hepatocytes and hepatocyte cancer cell lines preferentially engulf CD4+ T cells, which remained viable in hepatocytes." (PMID 31693899, 2019). "Together with the upregulation of MHCII+ expression on cancer cells, this phenomenon hints at a direct cytotoxic activity for the CD4+ T cells." (PMID 31362778, 2019). "A prospective phase 1 study of pembrolizumab in PLWH with a CD4 count >100 cells/μl and advanced cancer demonstrated evidence of safety and activity in KS, NHL, lung cancer, and liver cancer." (PMID 31555284, 2019). "Our data suggest that these CD4+ T cells can kill cancer cells directly via granzyme B-mediated cytotoxicity." (PMID 31362778, 2019). "The risk of many HIV-associated malignancies decreases with improved CD4 count on ART and cancer-specific mortality correlates inversely with CD4 count." (PMID 31555284, 2019). "We found that the suppressive phenotype of CD4+ T cells in PDA are distinct compared with other cancers." (PMID 30926808, 2019). "Although CD8+ T cells have been recognized as the major effector cells for T-cell cancer immunity, it has become controversial to adopt CD4+ or CD8+ T cells to generate CAR-T cells." (PMID 31379876, 2019). "RGMB expression levels negatively correlated with CD8 T cell abundance (25 of 33 cancers, p = 0.003), as well as with activated memory CD4+ T cells (26 of 33 cancers, p = 0.001)." (PMID 31061392, 2019). "Double staining for FOXP3 and CD4 showed that Foxp3+CD4+ cells were increased in cancer tissues of laparotomy group." (PMID 30216450, 2019). "CD4+ T cells can eliminate cancer cells directly in a perforin/granzyme B-dependent manner or indirectly via myeloid cells and/or NK cells." (PMID 31362778, 2019). "The abundance of these cells and their expression of PD-1 in MEs were comparable in different types of cancer, although it is worth noting that there were more Treg cells than there were CD4+ or CD8+ Tconv cells expressing PD-1." (PMID 31801611, 2019). "In the tissue, CD4+/IL-4+ and CD20+/IL-10+ cells were positively associated with miR-21 and CD4+/IFN-β, thyroid hormone, and cancer signaling pathways were shared between miR-21, miR-31, miR-23b, miR-146a, miR-1246, and miR-150." (PMID 32082077, 2019). "The lack of host leukocyte-derived IL-30 inhibits Tregs expansion, promotes intra-tumoral infiltration of CD4+T lymphocytes and cancer cell apoptosis." (PMID 31366386, 2019). "CD4+ T helper cells have a key role in the inflammatory processes in cancers via secretion of a set of cytokines." (PMID 31579438, 2019). "Anti-cancer activated memory CD4+ T cells were significantly lower in all recurrence groups, and anti-cancer γδT cells were significantly lower and pro-cancerous regulatory T cells were significantly higher in Early and Late compared to Survivors." (PMID 31729458, 2019).
cancer (continued). "Nuclear factor FoxP3 is the most important part in the specification of Treg cells, so both the percentage and their general number among CD4-positive cells in the blood and cancer tissue were established according to this factor." (PMID 30944830, 2019). "The number of activated memory CD4+ T cells, activated DCs and naive CD4+ T cells was increased in ER-negative cancers, while more resting mast cells and resting memory CD4+ T cells existed in ER-positive cancers." (PMID 31762828, 2019). "There are accumulating data showing that CD25+CD4+Treg cells antagonistically suppress antitumor immune effects in different types of malignancies." (PMID 30693029, 2019). "The development of cancers in immunosuppressed patients has demonstrated the contribution of different T cell populations, including CD4+ cells, in the control of cancer occurrence." (PMID 30922400, 2019). "Recently, a CD4-based CAR that was re-engineered (see details below) to incorporate lessons learned from successful cancer targeting CARs, was shown to confer greater antiviral activity than widely-investigated broadly neutralizing antibody (BNAb) based CARs." (PMID 31611880, 2019). "Monitoring of HIV, HBV and HCV viral load as well as CD4 count for PLWH during cancer treatment is necessary for patient safety and should be part of standard care for these patients." (PMID 31847881, 2019). "Utilizing the CIBERSORT algorithm, we showed that anti-cancer lymphocytes, memory CD4+ T cells and γδT cells, were significantly lower, and pro-cancerous regulatory T cells were significantly higher in Late tumors compared to Survivors." (PMID 31729458, 2019). "As in patients with cancer tissue, the expression of IC-molecules in CD4+ and CD8+ T cells was much higher in lung TM than in PB or spleen." (PMID 31801611, 2019). "IL-9-producing CD4+ helper T cells (Th9 cells) are a subset of CD4+ helper T cells with proinflammatory functions and anti-cancer properties in vivo." (PMID 31412566, 2019). "We observed a very closed correlation between high expression of CD45RC on CD4+ and CD8+ T cells suggesting that patients at higher AR risk have a lower cancer risk." (PMID 30925186, 2019). "Despite the critical roles of Th1-polarised CD4+ T cells in cancer immunosurveillance, the translation of their potential to clinical use remains challenging." (PMID 31358938, 2019). "Cancer antigens are then presented to T cells (CD4+ and CD8+ T lymphocytes) which enable a potent anticancer adaptive immune response." (PMID 31041312, 2019). "CD8+ and CD4+ T cells, albeit the effects are different, involve in cancer dormancy and metastases prevention via both immune and non-immune mechanisms." (PMID 31297335, 2019). "HLA-II molecules are mainly expressed on professional antigen presenting cells (APCs) and present peptides to CD4 T-cells, which have been shown to play a role in cancer cell recognition and killing." (PMID 31735170, 2019). "The difference remained significant when analysis was done according to cancer subtype for CD4+CD45RChigh T cells frequency, while CD8+CD45RChigh T cell frequency was no longer different between patients with or without solid cancer/PLTD." (PMID 30925186, 2019). "CD4, a type of T lymphocyte, is considered to be one of the most effective immune cells for eliminating cancer cells." (PMID 31817179, 2019). "Utilizing the CIBERSORT algorithm, we showed anti-cancer lymphocytes, memory CD4+ T cells and γδT cells, were significantly lower, and pro-cancerous regulatory T cells were significantly higher in Late tumors compared with Survivors." (PMID 31729458, 2019). "These unique features instill a specific immune state that affects microglia and infiltrated CD4+ T cells, generating a specific response to LPS that resembles some of the strategies that cancer cells use to escape immune surveillance." (PMID 31757220, 2019).
cancer (continued). "In cancers, Tregs represent one of the most important T cell populations as they are able to suppress the activation and/or expansion of antitumor CD4 and CD8 T cells through cell–cell contact or by cytokine release." (PMID 30889935, 2019). "We next compared the estimated fractions of this cell type (“T.cells.CD4.memory.activated”) among those cancer types, (i.e., LUAD, KIRC, PRAD, and THCA)." (PMID 30956779, 2019). "This PD-1 blockade was initially used in cancer treatment but has been shown to reduce CD4 T cell HIV reservoirs ex vivo." (PMID 31921023, 2019). "This method is widely used to distinguish true Tregs from other T cell populations which transiently upregulate FOXP3 after their activation and it showed that the CD4+Foxp3hiTbethi cells found in HPV-driven cancers represent bona fide Tregs." (PMID 30658697, 2019). "Another cytokine that is CD4 T cell-specific and important in cancer setting is Interleukin 21 (IL-21)." (PMID 31186477, 2019). "Current neoantigen-based cancer vaccines confer therapeutic benefits largely through neoantigen-specific CD4+ T cells." (PMID 31749795, 2019). "In contrast, expression of CD127 was downregulated in CD4+ T cell populations in cancer septic mice relative to previously healthy control mice." (PMID 29338031, 2018). "For instance, aberrant expression of proteins or peptides with specific post-translational modifications detected in cancer (e.g., phosphorylation, acetylation, and citrullination) have been shown to trigger CD4 and CD8 T-cell responses." (PMID 30097571, 2018). "In the wildtype mice, levels of CD4+ cells expressing IFN-γ declined at the later stages during the onset of cancer, while in the IL-23R KO mice, the levels of these cells remained constant throughout the course of lesion development and progression." (PMID 29664967, 2018). "Interleukins are small proteins secreted mainly by CD3+ and CD4+ T lymphocytes that mediate the "essential for cancer progression" interactions between cells." (PMID 30648081, 2018). "Recent studies have also highlighted a potential role for CD4+ T cells for the development of cancer immunotherapies." (PMID 30446001, 2018). "Mixed-effects and Cox regression models were used to examine associations between nadir or recent CD4, CD8, and white blood cell (WBC) counts or CD4:CD8 ratios and subsequent diagnosis of virus-associated cancers." (PMID 30315476, 2018). "While T cell exhaustion for CD8 cells is quite well described, much less is known about exhaustion of CD4 T cells in cancer." (PMID 29032503, 2018). "In this multisite cohort study of HIV patients diagnosed with cancer across Latin America, we found that age, time since HIV diagnosis, and detectable viral load were predictive of mortality after accounting for cancer type, sex, cART use, and CD4 count." (PMID 29760767, 2018). "While CD8+ T cells were modestly increased, we identified a significant increase in the absolute number of CD4+ T cells in cancer septic hosts as compared to previously healthy controls." (PMID 29338031, 2018). "While CD8+ T cells are in the spotlight of cancer immunotherapy, significant numbers of CD4+ T cells can also be found in solid tumors." (PMID 30505306, 2018). "Few papers correlated the two ligands to CD4+CD25+Foxp3+ expansion in inflammation and in pancreatic tumors, thus suggesting Jagged as an important area of investigation in cancer-associated Tregs." (PMID 30364244, 2018). "Median CD4 count at cancer diagnosis was 148 cells/μL (IQR 44–364), ranging from 82 cells/μL for patients in FH/HF-Argentina to 190 cells/μL in FIOCRUZ-Brazil." (PMID 29760767, 2018). "The function of CD4+ T lymphocytes in cancer has recently been extensively studied in both animal models and patients." (PMID 30069490, 2018). "The use and strengthening of the immune system via DCs and CD4+ T cell activation, which are suppressed by cancer cells in many cases, can be an effective strategy in cancer immunotherapy." (PMID 28944998, 2018).